PSMA1 (proteasome 20S subunit alpha 1)
Description:
Component of the 20S core proteasome complex involved in the proteolytic degradation of most intracellular proteins. This complex plays numerous essential roles within the cell by associating with different regulatory particles. Associated with two 19S regulatory particles, forms the 26S proteasome and thus participates in the ATP-dependent degradation of ubiquitinated proteins. The 26S proteasome plays a key role in the maintenance of protein homeostasis by removing misfolded or damaged proteins that could impair cellular functions, and by removing proteins whose functions are no longer required. Associated with the PA200 or PA28, the 20S proteasome mediates ubiquitin-independent protein degradation. This type of proteolysis is required in several pathways including spermatogenesis (20S-PA200 complex) or generation of a subset of MHC class I-presented antigenic peptides (20S-PA28 complex).
Synonyms: HC2; NU; PROS30; MGC14542; MGC14575; MGC14751; MGC1667; MGC21459; MGC22853; MGC23915; HEL-S-275
Tractability: Small molecule: an approved drug acts on it; a structure with a bound ligand is known; a high-quality ligand is known; it belongs to a druggable protein family. PROTAC: UniProt records ubiquitination sites on it; ubiquitination databases record sites on it; its protein half-life has been measured; a small molecule that binds it is known.
Gene: Protein-coding gene on chromosome 11 (14,504,211 to 14,643,635, reverse strand). Ensembl gene ENSG00000129084.
Subcellular location: Cytoplasm; Nucleus
Subcellular location (Human Protein Atlas): Nucleoplasm; Centrosome; Nuclear bodies
Pathways (Reactome):
Immune System: AMPK-induced ERAD and lysosome mediated degradation of PD-L1(CD274); Activation of NF-kappaB in B cells; Antigen processing: Ub, ATP-independent proteasomal degradation; Antigen processing: Ubiquitination & Proteasome degradation; CLEC7A (Dectin-1) signaling; Cross-presentation of soluble exogenous antigens (endosomes); Dectin-1 mediated noncanonical NF-kB signaling; Downstream TCR signaling; ER-Phagosome pathway; FCERI mediated NF-kB activation; GSK3B-mediated proteasomal degradation of PD-L1(CD274); Interleukin-1 signaling; NIK-->noncanonical NF-kB signaling; SPOP-mediated proteasomal degradation of PD-L1(CD274); TNFR2 non-canonical NF-kB pathway
Cell Cycle: APC/C:Cdc20 mediated degradation of Securin; APC/C:Cdh1 mediated degradation of Cdc20 and other APC/C:Cdh1 targeted proteins in late mitosis/early G1; Autodegradation of Cdh1 by Cdh1:APC/C; Autodegradation of the E3 ubiquitin ligase COP1; Cdc20:Phospho-APC/C mediated degradation of Cyclin A; FBXL7 down-regulates AURKA during mitotic entry and in early mitosis; G2/M Checkpoints; SCF(Skp2)-mediated degradation of p27/p21; SCF-beta-TrCP mediated degradation of Emi1; Separation of Sister Chromatids; The role of GTSE1 in G2/M progression after G2 checkpoint; Ubiquitin-Mediated Degradation of Phosphorylated Cdc25A; Ubiquitin-dependent degradation of Cyclin D
Signal Transduction: Asymmetric localization of PCP proteins; Degradation of AXIN; Degradation of DVL; Degradation of GLI1 by the proteasome; Degradation of GLI2 by the proteasome; Degradation of beta-catenin by the destruction complex; GLI3 is processed to GLI3R by the proteasome; Hedgehog 'on' state; Hedgehog ligand biogenesis; MAPK6/MAPK4 signaling; Negative regulation of NOTCH4 signaling; Regulation of PTEN stability and activity
and 28 more pathways
Gene Ontology:
Molecular function: protein binding; structural constituent of proteasome; lipopolysaccharide binding
Biological process: proteasomal protein catabolic process; proteasome-mediated ubiquitin-dependent protein catabolic process; regulation of proteasomal protein catabolic process; response to oxidative stress; apoptotic process; CD8-positive, alpha-beta T cell differentiation; CD8-positive, alpha-beta T cell homeostasis; cellular response to type I interferon; DNA damage response; DNA repair; flagellated sperm motility; immune system process; meiotic cell cycle; negative regulation of regulatory T cell differentiation; positive regulation of interleukin-2 production; positive regulation of tumor necrosis factor production; positive regulation of type II interferon production; proteasomal ubiquitin-independent protein catabolic process; regulation of G1/S transition of mitotic cell cycle; response to type II interferon; spermatogenesis; T-helper 1 cell differentiation; T-helper 17 cell differentiation; thymic T cell selection; negative regulation of inflammatory response to antigenic stimulus; and 2 more
Cellular component: cytoplasm; extracellular exosome; nuclear body; nucleoplasm; nucleus; proteasome complex; proteasome core complex; cytosol; proteasome core complex, alpha-subunit complex; proteasome storage granule; spermatoproteasome complex; synaptic vesicle
Genetic constraint (gnomAD): Loss-of-function variants: 2 observed, 18.37 expected, observed/expected ratio (o/e) 0.11, 90% interval 0.044 to 0.34. The upper end of that interval is the gene's LOEUF score, 0.34, which puts it in group 1 of 6, group 1 being the genes least tolerant of losing a copy. Missense variants: 170 observed, 244.38 expected, observed/expected ratio (o/e) 0.7, 90% interval 0.61 to 0.79. Synonymous variants: 80 observed, 82.03 expected, observed/expected ratio (o/e) 0.98, 90% interval 0.81 to 1.17.
Homologues: Orthologues: rabbit PSMA1 (100% identical), chimpanzee PSMA1 (99% identical), dog PSMA1 (99% identical), guinea pig PSMA1 (99% identical), pig PSMA1 (99% identical), mouse Psma1 (98% identical), macaque PSMA1 (94% identical), tropical clawed frog psma1 (93% identical), rat Psma1 (91% identical), zebrafish psma1 (91% identical), Drosophila melanogaster Prosalpha6 (53% identical), Caenorhabditis elegans pas-6 (53% identical), and 1 more. Paralogues in human: PSMA8 (32% identical), PSMA7 (32% identical), PSMA4 (29% identical), PSMA2 (29% identical), PSMA5 (28% identical), PSMA3 (25% identical), PSMA6 (25% identical), PSMB7 (19% identical), PSMB10 (18% identical), PSMB3 (17% identical), PSMB11 (16% identical), PSMB5 (16% identical), and 6 more.
Diseases named in the same sentence as PSMA1 in open-access papers:
PSMA1 is named in the same sentence as 60 diseases in open-access papers, as found by Europe PMC text mining. Sharing a sentence is not in itself a finding about the gene and the disease. The quoted sentences say what the papers report.
prostate carcinoma (11 papers, 2019 to 2025). A carcinoma that arises from epithelial cells of the prostate gland. "Future works are needed to validate the use of PSMA-1-MMAE-IR700 for FIGS and the immune response caused by PSMA-1-MMAE-IR700 treatment using an immunocompetent mouse model of prostate cancer that overexpresses PSMA." (PMID 35265213, 2022). "In summary, the synthesis of PSMA-1-MMAE-Pc413 represents a significant advancement in the treatment of prostate cancer." (PMID 39000194, 2024). "We are currently exploring the immune response after PSMA-1-MMAE-Pc413 or PSMA-1-Pc413 therapy in immune-competent animal models of prostate cancer." (PMID 39000194, 2024). "We have previously demonstrated that PSMA-1-Pc413 can provide effective adjuvant PDT after the image-guided surgery of prostate cancer, resulting in surgical cures." (PMID 39000194, 2024). "This surgical study highlights FIGS and PDT, specifically using PSMA-1-Pc413 as a promising strategy for enhancing surgical efficacy in the treatment of prostate cancer." (PMID 39000194, 2024). "In in vivo studies, PSMA-1-MMAE-Pc413 dramatically improves the therapeutic outcome for prostate cancer by providing a synergistic effect that surpasses the efficacy of each treatment modality alone in PC3pip tumors." (PMID 39000194, 2024). "Recently, a high-affinity PSMA-targeting ligand (PSMA-1) was developed, and it demonstrated its use in prostate cancer imaging and photodynamic therapy." (PMID 36860645, 2023). "Specifically, 177Lu-PSMA-1 is used in the treatment of castration-resistant prostate cancer that is ineffective or intolerant to the latest generation of chemotherapy and/or hormone therapy." (PMID 35631349, 2022). "The therapeutic profile of the PSMA-1-VcMMAE encourages further clin-ical development for the treatment of advanced prostate cancer." (PMID 33499427, 2021). "We next investigated the efficacy of PSMA-1-VcMMAE in mice bearing orthotopic PC3pip tumors, which mimic human prostate cancer in a more realistic way." (PMID 33499427, 2021). "To show versatility of the antitumor activity of PSMA-1-VcMMAE, we also tested it in mice bearing heterotopic C4-2 tumors, which are androgen-independent prostate cancer cells endogenously expressing PSMA." (PMID 33499427, 2021). "Prostate-Specific Membrane Antigen (PSMA) targeted radiosensitizers are developed for prostate cancer CT imaging and radiotherapy based on gold nanoparticles and a high-affinity targeting peptide, PSMA-1, revealing a size-dependent pattern." (PMID 31588336, 2019). "Another study revealed that PSMA1 promotes gastric cancer (GC) progression and proliferation by mediating deubiquitinase activity, suggesting that PSMA1 is a potential therapeutic target for GC, which further supports our findings that PSMA1 facilitates prostate cancer progression." (PMID 40901472, 2025). "Notably, we also established a prostate cancer organoid model to further demonstrate the effect of PSMA1 in neutrophils on PCa progression." (PMID 40901472, 2025). "Also, kidney uptake can be avoided by surface modification (such as by PSMA-1 peptide), which is preferable in prostate cancer therapy." (PMID 39711799, 2024). "In this study, we have exploited this higher-affinity ligand, PSMA-1, to selectively deliver the very potent microtubule disruption drug, monomethyl auristatin E (MMAE), to prostate cancer cells." (PMID 33499427, 2021). "The PSMA-1-VcMMAE was proven to have in vivo efficacy for different tumor cell lines and different mouse models of human prostate cancer, including metastatic disease, with little to no systemic toxicity." (PMID 33499427, 2021). "PSMA1, MRAS, LEP, SLC30A3, and RNF7 were found closely related with prostate cancer." (PMID 32528533, 2020).
breast carcinoma (10 papers, 2012 to 2021). "PSMA1 has been reported to be overexpressed in breast cancer, and PSMA1 gene expression levels have been reported to be upregulated in a neuroendocrine pulmonary tumor animal model." (PMID 29423100, 2018). "In the present study, we found that high expression of PSMA1-4 and PSMA6-7 was significantly associated with worse prognosis in breast cancer, while PSMA5 was related to better OS, RFS and DMFS." (PMID 27966459, 2017). "PSMA1 is a subunit of the proteasome complex and was reported to be upregulated in breast cancer cells." (PMID 23283305, 2012). "For example, EPB41, PSMA1, LEP, LECT2, and ZNF35 were associated with breast cancer." (PMID 32528533, 2020). "In this context, Deng and colleagues demonstrated that the expression of six proteasome subunits including PSMA1, PSMB5, PSMD1, PSMD2, PSMD8 and PSMD11 was increased over three-fold in breast cancer tissues when compared to adjacent normal tissues." (PMID 27966459, 2017). "For both PSMA1 and PSMA2, no datasets revealed significant difference between the breast cancer group and normal tissue group." (PMID 27966459, 2017).
colon cancer (6 papers, 2018 to 2024). "It has been demonstrated in gastric and lung cancer tissues that PSMA1 is upregulated, and PSMA1 is a biomarker of colon cancer." (PMID 38732562, 2024). "Overall, expression of maspin, ANXA3, LAP3, and PSMA1 was increased in colon cancer tissue extracts." (PMID 29423100, 2018). "Semi-quantitative assessment of PSMA1 expression yielded an average score of 3 for colon cancer and 1.7 for normal colonic mucosa." (PMID 29423100, 2018). "PSMA1 expression was markedly increased in colon cancer tissue, although it was also detectable in normal colonic mucosa." (PMID 29423100, 2018). "All 8 colon cancer tissue showed strong immunoreactivity with PSMA1." (PMID 29423100, 2018). "Of these, maspin, ANXA3, LAP3, and PSMA1 were reproducibly discovered as serum-reactive in all 3 initially tested cancer samples, including colon tumor tissue from the 2 patients and the liver metastatic tissue from the patient with primary colon cancer and secondary liver metastasis." (PMID 29423100, 2018). "A few examples of TAAs identified using proteomics include the markers PSMA1, LAP3, ANXA3, and maspin, which were identified by one group as biomarkers for colon cancer." (PMID 30804938, 2019). "We then used this approach to discover a set of cancer-immunogenic proteins in colon cancer (maspin, ANXA3, LAP3, and PSMA1) and showed that these proteins are overexpressed in the tumor, pointing to a possible abundance mechanism by which these proteins become immunogenic." (PMID 29423100, 2018).
gastric cancer (5 papers, 2017 to 2025). A primary or metastatic malignant neoplasm involving the stomach. "The present study aimed to reveal the functional significance of PSMA1 in gastric cancer (GC) progression and the underlying mechanisms." (PMID 36424389, 2022). "In survival analyses, PSMA1-7 showed significant prognostic value in breast, lung, and gastric cancer." (PMID 38166541, 2024). "In survival analyses based on Kaplan-Meier Plotter, PSMA1-7 showed significant prognostic values in breast, lung and gastric cancer." (PMID 27966459, 2017). "In Oncomine database, there were five datasets that compared the expression differences between gastric cancer and normal tissues for PSMA1-6, and four datasets for PSMA7." (PMID 27966459, 2017). "Recently, high expression of several of these PSM genes (e.g. PSMA1, PSMB4, and PSMD2) has been correlated with poor prognosis in a number of cancer types, including breast-, lung-, and gastric cancer." (PMID 36123629, 2022). "IHC scores showed that PSMA1 and TAZ proteins were expressed at significantly higher levels in gastric cancer tissue than that in adjacent normal tissue." (PMID 36424389, 2022).
colorectal cancer (4 papers, 2015 to 2024). A primary or metastatic malignant neoplasm that affects the colon or rectum. "Colorectal cancer cells, when treated with an anti-cancer compound, exhibited down-regulation of PSMA1." (PMID 38732562, 2024). "PSMA1 down-regulation has been detected in colorectal cancer cells after treatment with caffeic acid phenethyl ester and this has been shown to induce apoptosis of cancerous cells through the inhibition of NF-κB signaling." (PMID 26390031, 2015). "In colorectal cancer, PSMA1-5 and PSMA7 were demonstrated to be overexpressed in tumor tissues." (PMID 27966459, 2017). "In the TCGA database, PSMA1-5 and PSMA7 were overexpressed in colorectal cancer tissues examined by mRNA HiSeq expression data." (PMID 27966459, 2017).
lung carcinoma (4 papers, 2017 to 2025). "In contrast to A4GALT, CIB2, and PSMA1, high expression of IRF4 is associated with higher lung cancer patient survival." (PMID 33227088, 2020). "A4GALT, PSMA1, and CIB2 are all among the potential oncogenes identified, since high expression of their mRNAs is significantly associated with lower lung cancer patient survival." (PMID 33227088, 2020). "In lung cancer, PSMA1-2, PSMA4 and PSMA5 were correlated with better prognosis, whereas PSMA6 and PSMA7 predicted worse survival outcomes." (PMID 27966459, 2017). "High mRNA expression of PSMA1 and PSMA2 was significantly associated with PPS for lung cancer patients, with HR = 0.77 (0.60–0.99), p = 0.043 and HR = 0.65 (0.51–0.84), p < 0.001, respectively." (PMID 27966459, 2017). "With our thresholds (p-value = 0.01; fold change = 2; gene rank: 10%, data type: mRNA), none of the datasets revealed statistically significant differences between lung cancer group and normal tissue group for PSMA1 or PSMA4." (PMID 27966459, 2017).
melanoma (3 papers, 2016 to 2020). A malignant, usually aggressive tumor composed of atypical, neoplastic melanocytes. "PSMA1, PSMA3 and PSMA7 were significantly associated with survival outcomes in melanoma patients." (PMID 27966459, 2017). "Moreover, we also revealed that melanoma had higher levels of PSMA1 and PSMA3-6 compared with normal tissues." (PMID 27966459, 2017). "With respect to melanoma, the mRNA expression levels of PSMA1, PSMA3, PSMA5 and PSMA6 were upregulated in melanoma compared with normal tissues according to Haqq's dataset." (PMID 27966459, 2017).
acute myeloid leukaemia (2 papers, 2020 to 2021). "PSMA1, an α-ring component involved in the proteolytic degradation of most intracellular proteins, is downregulated by autophagic lysosome-induced TRAF6 degradation to inhibit the proteasome and result in apoptosis in acute myeloid leukemia." (PMID 34689164, 2021).
autoimmune disease (2 papers, 2013 to 2023). A disorder resulting from loss of function or tissue destruction of an organ or multiple organs, arising from humoral or cellular immune responses of the individual to their own tissue constituents. "The presence of antibodies against RPS13 and PSMA1 in different autoimmune diseases suggests that those autoantibodies are not specifically associated with MG, but could represent a phenomenon associated with autoimmunity in general." (PMID 23483977, 2013).
clear cell renal carcinoma (2 papers, 2017 to 2024). A malignant epithelial neoplasm of the kidney characterized by the presence of lipid-containing clear cells within a vascular network. "The expression levels of PSMA1-3 and PSMA6 were higher in kidney clear cell carcinoma than in normal samples." (PMID 27966459, 2017).
CNS cancer (2 papers, 2017 to 2022). "MDHDH reduced the protein level of MDH2 in glioma stem cells, and down-regulation of PSMA1 rescued the protein level of MDH2." (PMID 36527092, 2022). "Metabolism-related experiments (lactate, pyruvate, ECAR/OCR) also yielded the same conclusion, with all glioma cell lines with PSMA1 knockdown having more active metabolic functions." (PMID 36527092, 2022). "Next, we further investigated the role of PSMA1 in the regulation of the cellular behaviors of glioma cells." (PMID 36527092, 2022). "We further investigated whether PSMA1 influenced the MDHDH-mediated cellular behaviors of glioma cells." (PMID 36527092, 2022). "In addition, the immunofluorescence results indicate that upregulation of MDHDH promoted the colocalization of MDH2 and PSMA1 in glioma cells, further suggesting that MDHDH plays a role in the interaction between MDH2 and PSMA1." (PMID 36527092, 2022). "Western blot results of biomarkers associated with the AMPK/mTOR pathway in glioma stem cells are consistent with those in glioma cell lines: pathway alterations by MDHDH could be reversed by PSMA1 downregulation." (PMID 36527092, 2022). "There were 11 studies showing a significant statistical difference for PSMA1, of which 10 showed that mRNA expression level of PSMA1 was increased in tumor than normal tissues in seven kinds of cancers, while one regarding brain and CNS cancer showed an opposite result." (PMID 27966459, 2017). "PSMA1 could serve as a key effector in MDHDH-induced inhibition in glioma cells." (PMID 36527092, 2022). "The phenotypic reversion caused by knockdown of PSMA1 may be associated with the blocked degradation and increased protein levels of MDH2, suggesting that UPS may also be involved in the regulatory aspects of metabolic function in glioma cells." (PMID 36527092, 2022).
head and neck cancer (2 papers, 2017 to 2020). A primary or metastatic malignant neoplasm affecting the head and neck. "Combined with Oncomine and TCGA, the mRNA expression levels of PSMA1-7 were significantly upregulated in breast, lung, gastric, bladder and head and neck cancer compared with normal tissues." (PMID 27966459, 2017).